ZFYVE28 (zinc finger FYVE-type containing 28)
Description:
Negative regulator of epidermal growth factor receptor (EGFR) signaling. Acts by promoting EGFR degradation in endosomes when not monoubiquitinated.
Synonyms: KIAA1643; LST2; lst-2; LYST2
Tractability: Antibody: the Human Protein Atlas places it where antibodies can reach. PROTAC: UniProt records ubiquitination sites on it; ubiquitination databases record sites on it.
Gene: Protein-coding gene on chromosome 4 (2,269,582 to 2,418,651, reverse strand). Ensembl gene ENSG00000159733.
Subcellular location: Cytoplasm, cytosol; Early endosome membrane
Subcellular location (Human Protein Atlas): Cytosol; Plasma membrane; Nucleoplasm
Gene Ontology:
Molecular function: phosphatidylinositol-3-phosphate binding; protein binding; metal ion binding
Biological process: negative regulation of epidermal growth factor receptor signaling pathway; negative regulation of epidermal growth factor-activated receptor activity
Cellular component: cytosol; early endosome membrane
Genetic constraint (gnomAD): Loss-of-function variants: 40 observed, 76.91 expected, observed/expected ratio (o/e) 0.52, 90% interval 0.4 to 0.68. The upper end of that interval is the gene's LOEUF score, 0.68, which puts it in group 2 of 6, group 1 being the genes least tolerant of losing a copy. Missense variants: 1,321 observed, 1,242.3 expected, observed/expected ratio (o/e) 1.06, 90% interval 1.01 to 1.11. Synonymous variants: 612 observed, 547.36 expected, observed/expected ratio (o/e) 1.12, 90% interval 1.05 to 1.2.
Homologues: Orthologues: chimpanzee ZFYVE28 (99% identical), macaque ZFYVE28 (87% identical), mouse Zfyve28 (83% identical), rat Zfyve28 (82% identical), dog ZFYVE28 (80% identical), guinea pig ZFYVE28 (78% identical), pig ZFYVE28 (75% identical), tropical clawed frog zfyve28a (67% identical), zebrafish zfyve28 (61% identical), Drosophila melanogaster CG6051 (35% identical), Caenorhabditis elegans lst-2 (29% identical), Drosophila melanogaster CG31064 (12% identical). Paralogues in human: ZFYVE26 (14% identical), RUFY1 (13% identical), RUFY2 (12% identical), ZFYVE1 (11% identical), RUFY3 (11% identical), PLEKHM2 (10% identical), SNX29 (10% identical), ZFYVE16 (8% identical), ZFYVE19 (7% identical), PLEKHF1 (6% identical), PLEKHF2 (6% identical), RUNDC3A (6% identical), and 1 more.
Diseases named in the same sentence as ZFYVE28 in open-access papers:
ZFYVE28 is named in the same sentence as 11 diseases in open-access papers, as found by Europe PMC text mining. Sharing a sentence is not in itself a finding about the gene and the disease. The quoted sentences say what the papers report.
Insulin resistance (3 papers, 2023 to 2025). Increased resistance towards insulin, that is, diminished effectiveness of insulin in reducing blood glucose levels. "Overall, the liver-specific overexpression of Zfyve28 markedly impaired insulin sensitivity and led to worse metabolic and cardiovascular indicators associated with insulin resistance in mice." (PMID 37884540, 2023). "In summary, liver-specific knockout of Zfyve28 in mice significantly improved insulin sensitivity and other relevant indicators associated with insulin resistance." (PMID 37884540, 2023). "We then examined the effect of Zfyve28 liver-specific overexpression on other metabolic and cardiovascular indicators associated with insulin resistance in mice." (PMID 37884540, 2023). "While Zfyve28 overexpression impairs insulin sensitivity and causes lipid accumulation, Zfyve28 knockout in mice can significantly improve insulin sensitivity and other indicators associated with insulin resistance." (PMID 37884540, 2023). "We also investigate the effect of Zfyve28 on insulin sensitivity in mice, showing that Zfyve28 knockout in mice can significantly improve insulin sensitivity and other indicators associated with insulin resistance." (PMID 37884540, 2023). "In our study, while Zfyve28 liver-specific overexpression in mice impaired insulin sensitivity and caused an increase in lipid content in the serum and liver, Zfyve28 liver-specific knockout in mice significantly improved insulin sensitivity and other indicators associated with insulin resistance." (PMID 37884540, 2023). "ZFYVE28 may be a potential therapeutic target to improve insulin sensitivity and prevent metabolic and cardiovascular diseases associated with insulin resistance." (PMID 37884540, 2023). "While Zfyve28 liver-specific overexpression in mice impairs insulin sensitivity and causes an increase in lipid content in the serum and liver, Zfyve28 liver-specific knockout significantly improves insulin sensitivity and relevant indicators associated with insulin resistance." (PMID 37884540, 2023). "We proposed the mechanism by which ZFYVE28 is involved in insulin signaling and provided a potential therapeutic target to improve insulin sensitivity and prevent metabolic and cardiovascular diseases associated with insulin resistance." (PMID 37884540, 2023). "In addition, liver-specific Zfyve28 overexpression in mice impaired insulin sensitivity and caused an increase in lipid content in the serum and liver, while Zfyve28 liver-specific knockout in mice significantly improved insulin sensitivity and relevant indicators associated with insulin resistance." (PMID 37884540, 2023). "Two notable endosomal targets relevant to insulin resistance and type 2 diabetes are the Zfyve28 and Exoc6 genes." (PMID 39040474, 2024). "In this study, we first found lower ZFYVE28 expression in obese patients with normal insulin sensitivity, while higher expression was observed in MetS patients with insulin resistance." (PMID 37884540, 2023). "Insulin signaling inhibits ZFYVE28 expression by inhibiting NOTCH1 via the RAS/ERK pathway, whereas ZFYVE28 expression is elevated due to impaired insulin signaling in insulin resistance." (PMID 37884540, 2023). "Here, in our study, we found that ZFYVE28 expression was elevated in individuals with insulin resistance." (PMID 37884540, 2023). "In conclusion, we identify that ZFYVE28 is involved in insulin signaling and mediates insulin resistance by promoting phosphorylated insulin receptor degradation." (PMID 37884540, 2023). "Taken together, these findings suggested that ZFYVE28 expression was lower in obese subjects with normal insulin sensitivity, while it was elevated in subjects with insulin resistance." (PMID 37884540, 2023). "ZFYVE28 has great potential to be a therapeutic target to slow insulin receptor degradation and improve insulin resistance." (PMID 37884540, 2023).
Insulin resistance (continued). "Here, the authors show that ZFYVE28 is involved in insulin resistance by promoting the degradation of phosphorylated insulin receptor and ZFYVE28 may be a potential therapeutic target to improve insulin sensitivity." (PMID 37884540, 2023). "Overall, in this study, we reveal that ZFYVE28 is involved in insulin resistance by promoting phosphorylated insulin receptor degradation, and ZFYVE28 may be a potential therapeutic target to improve insulin sensitivity." (PMID 37884540, 2023). "Notably, ZFYVE28 is found to mediate insulin resistance, with higher expression levels in obese, non-diabetic patients (insulin resistant individuals)." (PMID 40656995, 2025). "Western blotting results showed that both insulin and KRA-533 could significantly inhibit the expression of ZFYVE28; however, under PA-induced insulin resistance, only KRA-533 had an inhibitory effect on ZFYVE28 expression while the inhibitory effect of insulin disappeared." (PMID 37884540, 2023).
bipolar disorder (1 paper, 2007). A disorder of the brain that causes unusual shifts in mood, energy, activity levels and the ability to carry out day-to-day tasks. "For example, 10 genes among the 16 confirmed genes (Cacng2, Dnajc3, Dusp4, Gpc6, Mbp, Nov, Phf21b, Atxn10, Xbp1, and Zfyve28) have their human orthologs located within a 10 Mb region flanking the linkage markers for bipolar disorder, and thus merit further study." (PMID 18028544, 2007).
breast carcinoma (1 paper, 2023). "Moreover, some studies have proposed a strong correlation between ZFYVE28 and breast cancer, gastric cancer and colon cancer." (PMID 37884540, 2023).
cancer (3 papers, 2020 to 2025). A tumor composed of atypical neoplastic, often pleomorphic cells that invade other tissues. "GNAQ and ZFYVE28 may be involved in the plasticity and metabolic regulation of cancer cells." (PMID 41231350, 2025).
renal disease (1 paper, 2018). "However, the ZFYVE28-deficient animals developed renal disease in a very similar way as the controls in this experimental setting." (PMID 29549365, 2018).
ZFYVE28 also shares sentences with these, for which no sentence is quoted: cardiovascular diseases (1 paper); gastric cancer (1); glomerulonephritis (1); infection (1); Intellectual disability (1); Obesity (1).